CCBE1 (collagen and calcium binding EGF domains 1)
Diseases named in the same sentence as CCBE1 in open-access papers (continued):
Sharing a sentence is not in itself a finding about the gene and the disease.
ovarian carcinoma (continued). "Chromatin remodelling also likely has a function, given that treatment with a de-acetylating agent also increased CCBE1 expression in the ovarian cancer cell lines." (PMID 19935792, 2010). "qPCR analysis of 78 primary ovarian carcinomas and 14 NOSE cell brushings determined that CCBE1 was significantly down-regulated in ovarian cancers of all histological subtypes as compared with NOSE (serous, mucinous, clear cell P<0.001; endometrioid P<0.05)." (PMID 19935792, 2010). "Approximately 41% (33/81) of ovarian carcinomas exhibited methylation in the CCBE1 promoter as compared with 20% (1/5) NOSE and 0% (0/4) normal ovarian stroma samples." (PMID 19935792, 2010). "CCBE1 promoter hypermethylation was detected in 6/11 (55%) ovarian cancer cell lines and 38/81 (41%) ovarian carcinomas." (PMID 19935792, 2010). "The frequent and early silencing of CCBE1 expression in ovarian cancer suggests that CCBE1 may have a function in its pathogenesis." (PMID 19935792, 2010). "To further expand this observation, we next wanted to determine whether re-expression of CCBE1 through a plasmid expression construct would inhibit migration of ovarian cancer cells." (PMID 19935792, 2010). "CCBE1 is thus a novel candidate TSG inactivated in early ovarian cancer development." (PMID 19935792, 2010). "As aberrant DNA methylation is a well-recognised mechanism of gene silencing in cancer, we next determined whether the putative promoter region of CCBE1 was methylated in ovarian cancer." (PMID 19935792, 2010). "CCBE1 maps to 18q21.32, a common region of loss of heterozygosity (LOH) in ovarian cancer that is associated with malignant progression of ovarian cancer and high tumour grade and poor survival." (PMID 19935792, 2010). "The microsatellite marker D18S64, located in the 3′ flanking region of CCBE1, shows 58% allelic loss in ovarian cancer, implying that LOH may also be an important mechanism involved in loss of CCBE1 expression; however, this remains to be determined." (PMID 19935792, 2010). "Analysis of oligonucleotide probesets correlating to CCBE1 in our earlier reported genome-wide transcriptional profiling study of primary ovarian carcinomas identified that CCBE1 expression was highly down-regulated in ovarian carcinomas of all histological subtypes as compared with normal ovary." (PMID 19935792, 2010). "To determine whether CpG island methylation directly mediates CCBE1 silencing, we compared CCBE1-expression levels in ovarian cancer cell lines before and after treatment with the methyltransferase inhibitor 5-aza-2′-deoxycytidine (5-AZA) with or without the histone deacetylase inhibitor TSA." (PMID 19935792, 2010). "There was a strong correlation between CCBE1 mRNA and protein levels: CCBE1 protein expression was only seen in HOSE 6.3 and 17.1 cells and in the ovarian cancer cell lines EFO27 and CoLo316 that retained the highest level of CCBE1 mRNA and protein." (PMID 19935792, 2010). "However, there was neither association of methylation with histological subtype, FIGO stage, tumour grade, age at diagnosis, pre-operative CA125 levels or ascites volume (data not shown), nor any association between CCBE1 methylation and earlier disease recurrence in women with ovarian cancer." (PMID 19935792, 2010). "CCBE1 resides distal to the tumour suppressor genes (TSG) DCC, SMAD2 and SMAD4, in a location suggested by microsatellite marker mapping to contain at least one additional as yet unidentified ovarian cancer TSG." (PMID 19935792, 2010). "Furthermore, we identified CCBE1 as a candidate TSG at least partly due to its genomic location at 18q21, a region of known LOH in ovarian cancer." (PMID 19935792, 2010). "As the ovarian cancer cell lines, which express endogenous CCBE1, do not form distinct colonies, we were unable to assess whether siRNA-mediated knockdown of CCBE1 would conversely promote survival." (PMID 19935792, 2010).
ovarian carcinoma (continued). "Moreover, expression of CCBE1 was not exclusively correlated with promoter methylation, suggesting that additional mechanisms contribute to its silencing in ovarian cancer." (PMID 19935792, 2010).
lung carcinoma (4 papers, 2019 to 2021). "In breast and lung cancers, CCBE1 has been shown to be a potential tumor suppressor, while in gastrointestinal stromal tumors (GISTs), CCBE1 enhances tumor angiogenesis." (PMID 33997050, 2021). "An investigation showed that in patients bearing lung cancer, CCBE1 expression is down-regulated within tumor tissue which is associated with poor prognosis." (PMID 34440261, 2021).
gastrointestinal stromal tumor (3 papers, 2021 to 2022). "In gastrointestinal stromal tumor patients, the patients with CCBE1 overexpression have worse overall survival and relapse-free survival compared with patients with CCBE1 under-expression." (PMID 35674190, 2022).
glioma (3 papers, 2019 to 2022). A benign or malignant brain and spinal cord tumor that arises from glial cells (astrocytes, oligodendrocytes, ependymal cells). "Third, the impact of the putative hsa_circ_0076931/miR-6760-3p/CCBE1 axis on glioma progression should be confirmed by rescue experiments." (PMID 34931668, 2022). "These experiments indicate that hsa_circ_0076931 might function as a sponge for miR-6760-3p to regulate CCBE1 in glioma progression." (PMID 34931668, 2022). "Finally, we verified the expression of miR-6760-3p and CCBE1 in vivo and their relationship with the prognosis of patients with glioma." (PMID 34931668, 2022). "In addition, compared with NBT, miR-6760-3p was notably up-regulated, whereas CCBE1 was dramatically down-regulated in glioma tissues as measured by qRT-PCR." (PMID 34931668, 2022). "Thus, we suggest that hsa_circ_0076931 overexpression can down-regulate miR-6760-3p and up-regulate CCBE1 in vivo, and miR-6760-3p and CCBE1 have relevance to the prognosis of glioma patients." (PMID 34931668, 2022). "Furthermore, we explored the effects of the miR-6760-3p/CCBE1 axis on glioma cells." (PMID 34931668, 2022). "Thus, we speculate that hsa_circ_0076931 might function as a sponge for miR-6760-3p to regulate CCBE1 in glioma progression." (PMID 34931668, 2022). "Therefore, the specific mechanism of CCBE1 in the progression of glioma tumors remains unclear." (PMID 34931668, 2022). "Therefore, miR-6760-3p and CCBE1 might be the regulatory mechanism of hsa_circ_0076931 in glioma." (PMID 34931668, 2022). "In the GEPIA database, we found that IKBIP was upregulated in glioma relative to normal tissue, while CCBE1, NRG1, and RGS4 were downregulated in glioma." (PMID 34897031, 2021). "It is important to acknowledge that several of the genes, including CCBE1, LOC102153127 and C18H7orf72, display negligible levels of expression in normal canine brain suggesting that downregulation in canine glioma may not be biologically significant." (PMID 31475119, 2019).
cholestasis (2 papers, 2013 to 2015). Impairment of the bile flow caused by obstruction within the liver, or outside the liver in the bile duct system. "The region on chromosome 18 contains 2 genes of particular interest, by functional and disease criteria: ATP8B1, mutated in some forms of cholestasis, and CCBE1 (collagen and calcium-binding epidermal growth factor domain-containing protein-1), essential for lymphangiogenesis in zebrafish and mouse." (PMID 24086631, 2013). "Mutations in CCBE1 may yield a phenotype not only of lymphatic dysplasia, but also of LCS or fetal hydrops; however, the possibility that the sibling with LCS also carries a homozygous mutation in an unidentified gene influencing cholestasis cannot be excluded." (PMID 24086631, 2013).
intestinal lymphangiectasia (2 papers, 2015 to 2020). Dilatation of the intestinal lymphatic system usually caused by an obstruction in the intestinal wall. "Testing should be directed by phenotype but CCBE1 sequencing should be considered in even apparently isolated cases of intestinal lymphangiectasia as the presence of lymphatic abnormalities outside of the gut may be subtle." (PMID 25925991, 2015).
liver cancer (2 papers, 2021). An epithelial or non-epithelial malignant neoplasm that arises from the liver. "Thus, our result indicates that CCBE1 might be also participating in the IPF progression and suggests that it could be contributing in the fibrogenesis associated with cancer, such as the fibrosis that precede the liver cancer appearance, an intriguingly phenomenon that should be addressed." (PMID 34440261, 2021).
lymph node metastasis (2 papers, 2021). "High expression of CCBE1 in rectal cancer is associated with tumor occurrence and differentiation, lymph node metastasis, and poor prognosis." (PMID 33997050, 2021). "Indeed, in the TCGA cohort CCBE1 expression was significantly higher in patients with lymph node metastasis compared to those without lymph node metastasis." (PMID 35126454, 2021).
Autoimmunity (1 paper, 2021). The occurrence of an immune reaction against the organism's own cells or tissues. "Our findings shed light on the CCBE1 gene's nsSNPs, protein 3D structure, PTM potential sites, and gene-gene interaction, and all of which may help researchers better understand the gene's role in autoimmunity and related diseases in the future." (PMID 34234628, 2021).
colon cancer (1 paper, 2023). "In particular, Song and colleagues have evidenced, in a colon cancer experimental model, that CCBE1 enhances VEGF-C and facilitates tube formation and the migration of LECs, promoting tumor lymphangiogenesis and consequently the lymphatic metastasis of colon cancer cells." (PMID 36979635, 2023).
congenital primary lymphedema (1 paper, 2016). "Sanger sequencing identified no pathogenic variants in the genes known to be associated with congenital primary lymphedema (i.e., CCBE1, VEGFR3, and VEGFC) in the UK proband (GLDUK:I.2)." (PMID 27400125, 2016).
endometrioid ovarian carcinomas (1 paper, 2010). "In addition, ISH provided visual evidence that CCBE1 mRNA expression is at least reduced in mucinous, serous, and endometrioid ovarian carcinomas as compared with normal ovary." (PMID 19935792, 2010).
fetal hydrops (1 paper, 2013). "In this study, homozygosity mapping identified a region containing a missense mutation in CCBE1 in 2 siblings, one with LCS and the other with fetal hydrops." (PMID 24086631, 2013). "CCBE1 mutation thus should be considered in the differential diagnosis when non-immune fetal hydrops recurs in a family." (PMID 24086631, 2013).
Hepatic failure (1 paper, 2015). "The underlying cause of Urioste syndrome remains unknown but it does seem unlikely to be associated with mutation in CCBE1 given the lack of any Mullerian abnormalities or hepatic failure in the known CCBE1 patients." (PMID 25925991, 2015).
hereditary lymphedema (1 paper, 2013). "Mutations in CCBE1 were reported in some patients with forms of hereditary lymphedema." (PMID 24086631, 2013).
Hernia (1 paper, 2020). "The results pointed out ACAN, MMPs, COLs, EPYC, VIT, CCBE1 and LGALS3 genes as strong candidates to trigger umbilical hernias in pigs, because they are involved in hernia related biological processes since the embryogenesis." (PMID 32379844, 2020).
hydrops (1 paper, 2013). "Our results extend the phenotype associated with CCBE1 mutation to encompass LCS, and confirm that CCBE1 mutation is present in some fetuses with hydrops." (PMID 24086631, 2013).
Inguinal hernia (1 paper, 2020). Protrusion of the contents of the abdominal cavity through the inguinal canal. "In humans, studies have shown that mutations in the CCBE1 gene are associated with genetic problems, including the occurrence of umbilical and inguinal hernias." (PMID 32379844, 2020).
Intellectual disability (1 paper, 2015). "The patient we describe here has a lymphatic dysplasia without intellectual disability or dysmorphism caused by mutation in CCBE1, highlighting the phenotypic variability that can be seen with abnormalities in this gene." (PMID 25925991, 2015).
lymphedema syndrome (1 paper, 2021). "Hennekam lymphangiectasia-lymphedema syndrome has been linked to single-nucleotide polymorphisms in the CCBE1 (collagen and calcium-binding EGF domains 1) gene." (PMID 34234628, 2021).
metastasis (1 paper, 2022). The spread or migration of cancer cells from one part of the body (where they first appeared) to another. "In CRC, CCBE1 overexpression is reported to be markedly associated with tumor differentiation, lymph node metastasis, vascular invasion, liver metastasis and TNM stage of CRC patients." (PMID 35674190, 2022).
prostate carcinoma (1 paper, 2021). A carcinoma that arises from epithelial cells of the prostate gland. "CCBE1 was originally identified in the chromosomal region of 18q21-qTER in breast and prostate cancer cell lines." (PMID 33997050, 2021).
prostate tumor (1 paper, 2023). "CRISP3 was upregulated; conversely, OGN, SPOCK3, COL4A6, CCBE1, and FLRT3 were downregulated in prostate tumor tissues." (PMID 37251946, 2023).
rheumatoid arthritis (1 paper, 2021). A chronic, systemic autoimmune disorder characterized by inflammation in the synovial membranes and articular surfaces. "CCBE1 ADAMTS3, VEGFC, FLTR4, and GJC2 are thought to be related with either Hennekam disorder or its related symptoms in many diseases, including rheumatoid arthritis." (PMID 34234628, 2021).
Umbilical hernia (1 paper, 2020). Protrusion of abdominal contents through a defect in the abdominal wall musculature around the umbilicus. "The results pointed out ACAN, MMPs, COLs, EPYC, VIT, CCBE1 and LGALS3 as strong candidates to trigger umbilical hernias in pigs since they act in the extracellular matrix remodeling and in the production, integrity and resistance of the collagen." (PMID 32379844, 2020). "From this set of genes, we highlight KRT14 (Keratin 14), CCBE1, ACAN, Desmoglein 2 (DSG2) and EPYC, which were more enriched in the anatomic development process in the gene network and were upregulated in animals affected by umbilical hernia." (PMID 32379844, 2020).
tumor (28 papers, 2010 to 2025). "Deletion of CCBE1 synergizes with vascular endothelial growth factor to promote tumor cell migration and is associated with reduced overall survival of patients." (PMID 37251946, 2023). "A recent study reported that CCBE1 was overexpressed in epithelial colorectal cancer (CRC) cells; however, the role of CCBE1 in tumor lymphangiogenesis and the mechanism underlying dysregulated CCBE1 expression in CRC remain undefined." (PMID 32089745, 2020). "The results showed that the expression of CCBE1 in GIST tumor tissues of the high risk groups was significantly higher than that of intermediate- and low-risk groups." (PMID 27506146, 2016). "Besides, high expression of CCBE1 is associated with tumor progression and drug resistance in gastrointestinal stromal tumor and colorectal cancer." (PMID 36906534, 2023). "CCBE1 expression is closely associated with tumor progression." (PMID 33997050, 2021). "High expression of CCBE1 is associated with tumor invasiveness and poor CRC prognosis." (PMID 33997050, 2021). "In addition to CRC cells, tumor stroma within CRC tissue shows high CCBE1 expression, which is associated with high lymphatic vessel density, increased lymph node metastasis and poor prognosis." (PMID 32089745, 2020). "PPI network analysis implicated CCBE1 and FCN3 as candidates for interaction with COLEC10, with their reduced expressions in tumor tissues and significant correlation with patient survival." (PMID 40026364, 2025). "They observed a significant downregulation of CCBE1 expression in tumors compared to non-tumor tissues, which was attributed to the high methylation of the CCBE1 promoter in HCC." (PMID 39179991, 2024). "The collagen and calcium binding EGF domains 1 gene (CCBE1), a proposed tumor suppressor, was increased in skin KS samples from those with KS alone whereas the gene expression was lower among those with KS with concurrent KAD (log2FC 0.39 vs. -1.29 p = 0.008)." (PMID 37740179, 2023). "As a possible tumor suppressor gene, the decreased expression of CCBE1 in those with concurrent KAD and KS (where KSHV viremia in the circulation is expected to be higher) requires further evaluation." (PMID 37740179, 2023). "The genes repressed in both GE1-HCC and GE2-HCC included those with supposed tumour-inhibiting activity, e.g. CXCL14, CCBE1, IGFBP1, RND3, BMP10 and COLEC10, which encode proteins involved in extracellular matrix remodelling, migration and the immune response." (PMID 33541355, 2021). "On the other hand, in epithelial cancer cells, TGFβ exerts its anti-tumor function by downregulating calcium-binding EGF domain-1 (CCBE1), which is essential for tumor lymphangiogenesis." (PMID 33408771, 2021). "Approximately 38.3% of CRC samples had high CCBE1 expression in both tumor cells and stroma, and these patients had the worst OS and DFS." (PMID 32089745, 2020). "Nuclear SMAD2 expression was found in tumor cells of 45% of CRC samples and in tumor stroma of 70% of cases, in which CCBE1 expression was significantly lower than in the samples with cytoplasmic SMAD2 staining." (PMID 32089745, 2020). "Based on the role of CCBE1 in VEGFC activation, it is rational that CCBE1 plays an oncogenic role, enhancing tumor lymphangiogenesis and lymphatic metastasis." (PMID 32089745, 2020). "Conversely, knockdown of CCBE1 in SW480 cells decreased the number of human mitochondrion protein-positive tumor cells in the LNs." (PMID 32089745, 2020). "To validate the biological function of CCBE1 in tumor lymphangiogenesis and lymphatic metastasis in vivo, we established a hindfoot lymphatic drainage model 22-25." (PMID 32089745, 2020). "Cancer-associated fibroblasts (CAFs) express and secret CCBE1, thereby contributing to VEGFC maturation and tumor lymphangiogenesis in CRC." (PMID 32089745, 2020). "Taken together, these data indicated that CCBE1 promotes tumor lymphangiogenesis and lymphatic metastasis in CRC in vivo." (PMID 32089745, 2020).